GPR55 (G protein-coupled receptor 55)
Diseases named in the same sentence as GPR55 in open-access papers (continued):
Sharing a sentence is not in itself a finding about the gene and the disease.
Cognitive impairment (7 papers, 2023 to 2025). Abnormal cognition is characterized by deficits in thinking, reasoning, or remembering. "The GPR55 agonist, O-1602, has displayed a potential in ameliorating cognitive impairment, neuroinflammation, oxidative stress, and apoptosis induced by lipopolysaccharide in mice, suggesting a neuroprotective role (Wang XS." (PMID 38895631, 2024). "Activation of GPR55 has been observed to mitigate cognitive impairment, oxidative stress, neuroinflammation, and synaptic dysfunction in AD mouse models." (PMID 38895631, 2024). "In AD mouse models, activation of GPR55 has been shown to reduce synaptic dysfunction, oxidative stress, neuroinflammation, and cognitive impairment." (PMID 38895631, 2024). "The role of Trpv-1 and GPR-55 activation in reducing Aβ-induced impairments and cognitive deficits is established." (PMID 39201317, 2024). "For example, O-1602, a synthetic GPR55 agonist reversed β amyloid-induced cognitive impairment and release of pro-inflammatory cytokines as well as the production of reactive oxygen species and cell death in mice, suggesting GPR55 as a promising target to treat AD." (PMID 40509339, 2025). "Notably, GPR55 activation has neuroprotective effects, as pharmacological stimulation of this receptor attenuates cognitive impairment, neurotoxicity, neuroinflammation, and synaptic dysfunction in AD mouse models." (PMID 41303637, 2025). "Thus, both approaches targeting Trpv-1 and GPR-55 demonstrated significant reductions in neuronal degeneration and cognitive impairments, although through different molecular pathways." (PMID 39201317, 2024). "Similarly, in an LPS-induced murine AD model, O-1602 reversed LPS-dependent downregulation of GPR55, cognitive impairment, and neuronal apoptosis." (PMID 38931342, 2024). "Interestingly, the GPR55 agonist O-1602 was recently reported to reduce cognitive deficits, pro-inflammatory cytokines and synaptic dysfunction in a mouse model of Alzheimer’s disease." (PMID 36701411, 2023).
prostate carcinoma (7 papers, 2015 to 2025). A carcinoma that arises from epithelial cells of the prostate gland. "Consistent with this, expression of both ABCC1 and GPR55 is detected in human prostate cancer cell lines PC3, DU145 and LNCaP." (PMID 32718079, 2020). "LPI produced and secreted by ovarian and prostate cancer cells has been shown to induce a GPR55-dependent autocrine loop regulating cancer growth." (PMID 25989290, 2015). "Activation of GPR55 can trigger cell signaling cascades that stimulate cell proliferation and migration in certain cell types, such as transformed thyroid cells, lymphoblastoid cells, breast cancer cells, and prostate cancer cells." (PMID 32121640, 2020). "The effects of CBD on cell viability werenot blocked by cannabinoid receptor antagonists, a transient receptorpotential vanilloid 1 (TRPV1) channel blocker, or an agonist of theG-protein-coupled receptor GPR55, suggesting that CBD acts independentlyof these targets in prostate cancer cells." (PMID 37703852, 2023). "We, herein, investigated whether gintonin could serve as a ligand for GPR40 and GPR55, using the insulin-secreting beta cell-derived cell line INS-1 and the human prostate cancer cell line PC-3, respectively." (PMID 32121640, 2020). "Here, we investigated the effects of gintonin on insulin release in INS-1 rat pancreatic beta cells and on cell migration of PC-3 prostate cancer cells, to elucidate whether gintonin can also act on GPR40 and GPR55." (PMID 32121640, 2020). "Treatment of these cells with GPR55 siRNA reversed these effects, suggesting that GPR55 may mediate LPI effects in ovarian and prostate cancer cells." (PMID 25926795, 2015). "Our group previously demonstrated that ABCC1 is involved in an autocrine loop by which prostate cancer cells can stimulate their own proliferation through the release of the lysophospholipid lysophosphatidylinositol (LPI) and activation of the G protein-coupled receptor GPR55." (PMID 32718079, 2020).
Alzheimer disease (6 papers, 2018 to 2023). A progressive, neurodegenerative disease characterized by loss of function and death of nerve cells in several areas of the brain leading to loss of cognitive function such as memory and language. "Targeting GPR55 might be a new therapeutic option to treat neurodegenerative diseases with a neuroinflammatory background such as Alzheimer’s disease, Parkinson, and multiple sclerosis (MS)." (PMID 30453998, 2018). "In a mouse model of Alzheimer’s disease induced by streptozotocin (STZ), activation of the G-protein-coupled receptor 55 (GPR55) has been found to have neuroprotective effects." (PMID 37801482, 2023). "The present study explores the expression of the ECB system, the ECB-related receptor GPR55, and cognitive functions (novel object recognition; NOR) in the 5xFAD (FAD: family Alzheimer’s disease) transgenic mouse model of AD." (PMID 33167441, 2020).
Hepatic steatosis (6 papers, 2019 to 2025). Steatosis is a term used to denote lipid accumulation within hepatocytes. "For instance, GPR55‐deficient mice show defective insulin signaling and a significant increase in liver fatty acid synthase, leading to hepatic steatosis." (PMID 39417398, 2024). "Extracellular LPI induces hepatic steatosis and directly activates the hepatic stellate cells (HSCs) in a GPR55-dependent manner." (PMID 40760121, 2025). "In several animal models of non-alcoholic hepatic steatosis and steatohepatitis, GPR55 was found to increase lipid content by inducing de novo fatty acid synthesis and decreasing fatty acid β oxidation, which is consistent with our results." (PMID 33803038, 2021). "G protein-coupled receptor 55 (GPR55) has not been extensively studied in hepatic steatosis, although its endogenous ligands have been implicated in liver disease progression." (PMID 33803038, 2021). "Our measurement of lysophosphatidylinositols also suggests that high-fat diets increase the levels of endogenous GPR55 agonists in the liver, which may activate GPR55 in hepatocytes and stellate cells, resulting in the development of hepatic steatosis and steatohepatitis." (PMID 33803038, 2021). "However, the role of GPR55 in liver diseases such as hepatic steatosis has not been much studied." (PMID 33803038, 2021).
Insulin resistance (6 papers, 2018 to 2023). Increased resistance towards insulin, that is, diminished effectiveness of insulin in reducing blood glucose levels. "Because of the proposed contribution of insulin resistance to AD progression, this further support the need of exploring the GPR55 contribution to AD." (PMID 37372090, 2023). "We must therefore look beyond increased adiposity and consequent insulin resistance to account for impaired glucose tolerance in our GPR55 knockout mice." (PMID 32904155, 2020). "The significance of GPR55 as a potential regulator of insulin action and energy homeostasis is further strengthened by the finding that GPR55−/− mice exhibit insulin resistance and increased adiposity." (PMID 30148676, 2019). "Only in vivo studies on the role of GPR55 in energy and glucose homeostasis have been performed in GPR55-/- mice, which revealed that GPR55 knockout, at least partially, increased adiposity and insulin resistance due to reduced physical activity." (PMID 33530406, 2021). "Consistent with the insulin resistance reported in these animals, GPR55−/− mice held without food for 6 h exhibit modest but significant hyperglycemia and hypertriglyceridemia." (PMID 30148676, 2019).
Parkinson disease (6 papers, 2018 to 2024). A progressive degenerative disorder of the central nervous system characterized by loss of dopamine producing neurons in the substantia nigra and the presence of Lewy bodies in the substantia nigra and locus coeruleus. "GPR55 and CB1 heteromers have also shown significant neuroprotection against parkinsonism-inducing toxins, as in AD." (PMID 38895631, 2024). "Additionally, the expression of heteromers consisting of GPR55 and CB1/CB2 receptors in the striatum has been evaluated in parkinsonian macaques, highlighting a correlation between Parkinsonism and altered expression of these heteromers." (PMID 38895631, 2024). "However, the GPR55 agonist abnormal-cannabidiol (Abn-CBD), a synthetic cannabidiol isomer, displayed beneficial properties when chronically administered (5 weeks) to a murine model of Parkinson’s disease." (PMID 31396087, 2019).
glioma (5 papers, 2021 to 2026). A benign or malignant brain and spinal cord tumor that arises from glial cells (astrocytes, oligodendrocytes, ependymal cells). "These authors also showed that the lower overall survival rate in 74 high-grade glioma patients correlated with higher GPR55 expression." (PMID 36497400, 2022). "GPCR components, including GPR56 41, GPR55 42 and many others, are dysregulated in human glioma and in other brain tumors." (PMID 34373757, 2021). "Additionally, changes in the expression profiles of PINK1 and GPR55 were observed in correlation with survival rates in high-grade vs. low-grade gliomas, suggesting potential alterations in inflammatory and metabolic profiles." (PMID 40565152, 2025). "In this study, in contrast to CNR1 and GPR55, TRPV1 mRNA negatively correlated with glioma grade and positively correlated with overall survival." (PMID 36497400, 2022). "First, we found up-regulated CNR1, GPR55, and TRPV1 expression in glioma patient-derived tissue samples and cell lines compared with non-malignant brain samples." (PMID 36497400, 2022). "The focus of the present research was to first determine CB1/CNR1, GPR55, and TRPV1 gene expression in glioma samples and in differentiated GBM cells and GSCs." (PMID 36497400, 2022). "CNR1 and GPR55 did not correlate with glioma grade, whereas TRPV1 negatively correlated with grade and positively correlated with longer overall survival." (PMID 36497400, 2022). "Highly expressed CNR1 and GPR55 genes in glioma and GBM vs. non-cancerous brain tissues did not correlate with increased malignancy or GBM subtype, respectively." (PMID 36497400, 2022). "First, CNR1 and GPR55 mRNA expressions between different degrees of glioma malignancy, i.e., low-grade glioma vs. GBM, were not significantly different, but were higher than those in non-malignant brain." (PMID 36497400, 2022). "Three major CNRs, highly specific CB1, less selective GPR55, and non-specific ion receptor protein TRPV1, are overexpressed in low-grade glioma and GBM vs. normal brain." (PMID 36497400, 2022). "The relative expression of CNR1, GPR55 and TRPV1 genes in tissues showed that the three cannabinoid receptor genes did not correlate to each other in glioma or in GBM tissues, meaning they were independently regulated." (PMID 36497400, 2022). "In glioma tissues, highly expressed CNR1 and GPR55 did not correlate with increased malignancy." (PMID 36497400, 2022).
hepatoma (5 papers, 2021 to 2023). "A lentivirus designed to stably overexpress GPR55 was constructed and transfected into hepatoma cell lines (HepG2-OE and 97H-OE) and its overexpression was confirmed by western blotting." (PMID 37688769, 2023). "Therefore, the functions of GPR55 were investigated in human Hep3B hepatoma cells and in mice fed a high-fat diet using O-1602, the most potent agonist of GPR55, and CID16020046, an antagonist of GPR55." (PMID 33803038, 2021). "Therefore, the functions of GPR55 were investigated in Hep3B human hepatoma cells and mice fed high-fat diets." (PMID 33803038, 2021). "First, we assessed the expression of GPR55 in human hepatoma cell lines Hep3B and HepG2." (PMID 33803038, 2021).
liver diseases (5 papers, 2021 to 2026). "We propose that targeting the endocannabinoidome, specifically the LPI/GPR55 axis, represents a promising therapeutic strategy for liver disease." (PMID 41823054, 2026). "The L-α-lysophosphatidylinositol/G protein-coupled receptor 55 (LPI/GPR55) axis, an element of the endocannabinoidome, has emerged as a key driver behind liver disease progression, leading to the progression of metabolic dysfunction associated steatohepatitis (MASH)." (PMID 41823054, 2026).
mental disorder (5 papers, 2021 to 2024). A disease that has its basis in the disruption of mental process. "The role of GPR55 in psychiatric disorders is still under investigation, but based on the signal pathways, GPR55 is associated with inflammatory responses modulated via this receptor." (PMID 38796643, 2024). "Association of a GPR55-mutation with psychiatric diseases has been shown in human clinical trials as well." (PMID 35055142, 2022). "GPR55 selective coumarin derivatives should therefore be further investigated for their potential use in inflammation-related neurological and psychiatric disorders." (PMID 38931342, 2024). "Keywords such as “GPR55”, “neuroinflammation”, “oxidative stress” and the different agonists, antagonists, and psychiatric disorders were chosen." (PMID 38796643, 2024). "A recent genome-wide study found that a mental disorder borderline personality disorder (BPD) and life adverse events were associated with the methylation status of several genes including GPR55." (PMID 37185752, 2023). "The featured studies indicate a complex role of GPR55 in neurological and psychiatric diseases, with the agonism, as well as the antagonism, being beneficial dependent on the concrete situation." (PMID 35055142, 2022). "In contrast to neuroinflammation, no studies specifically focus on the role of GPR55 in oxidative stress as a co-cause of psychiatric disorders." (PMID 38796643, 2024). "GPR55, a receptor considered part of the endocannabinoid system, has gained much attention in recent years because of its promising role in the modulation of neuroinflammation and the treatment of inflammatory-mediated neurological and psychiatric disorders." (PMID 38931342, 2024). "Additionally, a link between the upregulation of GPR55 and mental disorders has been reported." (PMID 37185752, 2023). "Furthermore, the role of the G-protein coupled receptor 55 (GPR55) in inflammatory and oxidative pathomechanisms and, therefore, treatment of psychiatric disorders will be discussed." (PMID 38796643, 2024). "In suicide victims without any diagnosed mental illness, decreased GPR55 and CB2 gene expression with increased GPR55-CB2 heteromers were found in the dorsolateral prefrontal cortex (DLPFC), eliciting a potential involvement of GPR55 in impulsivity and decision-making in suicide." (PMID 35055142, 2022).
skin cancer (5 papers, 2016 to 2023). "Studies involving humans and mice have shown that GPR55 promotes skin tumor development by enhancing invasiveness and tumorigenicity." (PMID 35873682, 2022). "Conversely, silencing RNA and microRNA miR-675-5p GPR55 knockdown studies, have shown that cancer cell proliferation and colony development in skin carcinoma and non-small lung cancer cells, respectively, is inhibited." (PMID 34324032, 2021). "GPR55, for example, has been reported to be upregulated in human squamous cell carcinomas and to enhance skin cancer cell anchorage-independent growth, invasiveness and tumorigenicity in vivo." (PMID 28288630, 2017).
type 2 diabetes (5 papers, 2015 to 2020). "Further support for the potential of GPR55 agonists in the treatment of type 2 diabetes comes from two studies that have found that the GPR55 agonist O-1602 stimulated insulin secretion from wild-type but not GPR55 -/- murine islets of Langerhans." (PMID 32904155, 2020). "Despite many differences in details between the findings of those who have studied GPR55 knockout mice, including ourselves, we agree that GPR55 agonists might be of value in the treatment in type 2 diabetes." (PMID 32904155, 2020). "Moreover, GPR55 expression has been found to be increased in adipose tissue of obese individuals and further so in obese patients with type 2 diabetes, with GPR55 expression correlating with body weight, BMI and percentage fat mass." (PMID 27677765, 2016). "Understanding the role of GPR55 in energy homeostasis may provide a novel target for therapeutic intervention in type-2 diabetes." (PMID 25926795, 2015). "Furthermore, novel receptors GPR55 and GPR119 have recently been shown to affect blood glucose control, and activation of these receptors with novel synthetic fatty acids may have therapeutic potential for type 2 diabetes." (PMID 27677765, 2016).
Arthritis (4 papers, 2016 to 2025). Inflammation of a joint. "A study on rodents has shown that the peripheral activation of GPR55 can reduce mechanosensitivity in the event of joint inflammation." (PMID 36937015, 2023). "Thus, CID16020046 suppresses the CIA-induced increase in arthritis score and foot thickening by inactivating GPR55." (PMID 40429822, 2025). "Therefore, targeting GPR55 in chondrocytes may represent a potential therapeutic approach for slowing down cartilage destruction in dogs with arthritis, thus enhancing the welfare of older dogs, those most affected by spontaneous OA, using a molecular antagonist such as CBD." (PMID 37760233, 2023).
Dravet syndrome (4 papers, 2020 to 2024). "RNA-seq analysis of an Scn1a+/- mouse model of Dravet syndrome identified Gpr55 as a candidate genetic modifier." (PMID 36701411, 2023). "We first examined the effect of Gpr55 deletion on a hyperthermia-induced seizure, which models febrile seizures that occur in children with Dravet syndrome." (PMID 36701411, 2023). "Future research is needed using alternative approaches and additional probe drugs to further explore GPR55 as a new drug target for treating Dravet syndrome." (PMID 36701411, 2023). "Our results are inconsistent with the view that the anticonvulsant mechanism of action for CBD in Dravet syndrome is solely via blockade of GPR55." (PMID 36701411, 2023). "It acts as an antagonist of GPR55, reducing the frequency, severity, and duration of spontaneous seizures, which has been demonstrated and validated in a genetic mouse model of Dravet syndrome." (PMID 34834237, 2021). "The anticonvulsant action of CBD in a mouse model of Dravet syndrome was attributed to antagonism of GPR55, where CBD and the selective GPR55 antagonist CID16020064 similarly restored loss of inhibitory neurotransmission in the dentate gyrus and CID16020064 blocked the effects of CBD." (PMID 36701411, 2023). "We then determined whether heterozygous deletion of Gpr55 is anticonvulsant in the F1.Scn1a+/- mouse model of Dravet syndrome." (PMID 36701411, 2023). "In order to assess whether the increased Gpr55 expression of F1.Scn1a+/- mice contributes to the Dravet syndrome phenotype, we generated F1.Scn1a+/- mice with heterozygous deletion of Gpr55 (F1.Scn1a+/;Gpr55+/-)." (PMID 36701411, 2023). "Here we assessed whether Gpr55 contributes to the strain-dependent seizure phenotypes of the Scn1a+/- mouse model of Dravet syndrome." (PMID 36701411, 2023). "Here we sought to examine whether the orphan receptor Gpr55 could be a genetic modifier and potential novel drug target in the Scn1a+/- mouse model of Dravet syndrome." (PMID 36701411, 2023). "Moreover, our results suggesting Gpr55 might be a genetic modifier may be specific to our mouse model and future studies are needed to explore whether this translates to Dravet syndrome patients." (PMID 36701411, 2023). "The acidic form of CBD was studied for its anticonvulsant effect in a mouse model of Dravet syndrome, and it was found that CBDA exhibited significant anticonvulsant properties through a mechanism that could involve the 5-HT1A, GPR55, or TRPV1 receptors." (PMID 34834237, 2021). "Our results suggest that GPR55 antagonism may not be a suitable anticonvulsant target for Dravet syndrome drug development programs, although future research is needed to provide more definitive conclusions." (PMID 36701411, 2023). "Our study does have limitations, including that we could not ascertain the effects of homozygous deletion of Gpr55 on seizure phenotypes of the Scn1a+/- mouse model of Dravet syndrome." (PMID 36701411, 2023).